CD83 (CD83 molecule)
Diseases named in the same sentence as CD83 in open-access papers (continued):
Sharing a sentence is not in itself a finding about the gene and the disease.
infection (continued). "The aim of the present study was to evaluate the expression of different markers of DC (CD1b, CD83 and MHC-II) and of FDC (CNA.42, S100 and CD83) in the HLNs and liver of sheep during the early stages of infection with F. hepatica." (PMID 32131896, 2020). "FACS analysis results showed that the expression of CD83 on CD19+ peritoneal B cells was drastically increased at 3 h and then restored to basal level at 24 h after infection with live A/WSN/1933 virus." (PMID 33302987, 2020). "In an attempt to evaluate the infection of dendritic cells by EBV, we also analyzed the expression of the dendritic cell marker CD83 by the EBER+ cells." (PMID 30842768, 2019). "The generation of CD83+ and CCR7+ DCs (Mt-MoDCs) requires the infection of monocytes with live MTB, since infection with heat-killed bacteria partially abrogates the effects on monocyte differentiation." (PMID 30650615, 2019). "One of the most noteworthy findings of our study was the influence of the infection on peritoneal CD14, CD83 and MHCII cells over time." (PMID 30547823, 2018). "Regarding the dynamics of APC, a different tendency was observed during the early stage of infection for CD14, MHCII and CD83 cells." (PMID 30547823, 2018). "CD83 and MHCII cells developed an increasing trend during the early stage of infection, and were significantly decreased at the chronic stage of the infection." (PMID 30547823, 2018). "Peritoneal CD83 and MHCII cells developed an increasing trend during the early stage of infection, and showed a significant decrease at the late stage of the infection." (PMID 30547823, 2018). "CD83 can be expressed in the JPX-9 cell line by cadmium-mediated Tax1 induction and in Jurkat cells or PBMCs by Tax1 introduction via infection with a recombinant adenovirus carrying the Tax1 gene." (PMID 26129803, 2015). "To test the maturation status of NSR infected DCs, we analysed surface expression of MHC-I, MHC-II, CD40, CD80, CD83 and CD86 molecules upon infection." (PMID 26575844, 2015). "To assess the phenotypic changes induced by BCG-dHCM infection, we assessed the expression of MHC, CD86 and CD83 molecules on DC." (PMID 24690183, 2014). "Before infection, the immature DC phenotype (CD1a +, HLA-DR +, CD80 −, CD86 −, CD14 −, CD83−) was verified by flow cytometry (Figure A1)." (PMID 23970881, 2013). "Infection also induced the expression of co-stimulatory molecules such CD40, CD83, CD86, adhesion molecules (CD38, Itga5, and ICAM1), and tissue invasion molecules such as MMP12 and MMP14." (PMID 22928052, 2012). "DCs infected with live H37Ra displayed a mature phenotype, up-regulating CD83 and CD86 after 48 h infection with Mtb." (PMID 22024399, 2011). "Although infection induced CD80, CD83, CD86, and HLA class II expression on the surface of DCs, the activation of CD4+ T cells was impaired, which is consistent with findings in RSV-infected murine DCs, where the formation of immunological synapses was impaired." (PMID 41280933, 2025). "Expression of the activation marker CD83 on B cells was not consistent for all animals, although there was a detectable transient increase after the primary infection with ZIKV PR." (PMID 35493734, 2022). "HCMV-infected mature DCs treated with proteasome inhibitors had unchanged CD83 levels while non-treated HCMV-infected cells exhibited a significant decrease in surface CD83 levels within 12 h of infection, indicating that HCMV targets CD83 for proteasomal degradation." (PMID 34299120, 2021). "Similar to normal iDCs, upon infection with herpes simplex virus type 1 (HSV-1) LADIII iDCs downregulated CD83, a reaction that is proteasome-dependent and not known to require integrin signaling." (PMID 32596167, 2020). "After infection with H-1PV, the level of CD80 and CD86 rose 8-fold and CD83 2-fold." (PMID 31192129, 2019).
infection (continued). "Deficiency or knockdown of GDF15 in DCs increased the expression of MHCII, CD40,CD80 CD83, and CD86, while over expression of GDF15 either by using GDF15 TG DCs or infection with GDF15-Ad reduced the expression of these molecules, in comparison with WT untreated DCs." (PMID 30425709, 2018). "Additionally, we evaluated these maturation markers and CD83 on CD45.1+ DCs cultured over WT-, ΔgH-, and ΔgD-2-infected CD45.1− DCs 24 h after infection to determine the effect of infected DCs on bystander DCs." (PMID 29176979, 2017). "Results of infection kinetics and cycloheximide-actinomycin D-chase experiments, strongly suggested that an HCMV immediate early gene product is responsible for the induction of CD83 down-modulation." (PMID 28203230, 2017). "Together, these data suggest that NSR-infection does not result in increased proteasomal degradation of CD83." (PMID 26575844, 2015). "The results show that neither NSR infection, nor a combination of LPS stimulation and NSR infection significantly affected the total levels of CD83 mRNA, as compared to control stimulations." (PMID 26575844, 2015). "Inhibition of endocytosis at early time points after infection (6 hpi) only partially restored CD83 levels, while inhibition at later time points (12 hpi) did not result in restoration of CD83 levels." (PMID 26575844, 2015). "Thus, we propose a model where infection with NSR is sensed by DCs, resulting in surface exposure of CD83 originating from intracellular pools." (PMID 26575844, 2015). "The numbers of langerin+ DCs, DC-SIGN+ DCs, and CD83+ DCs were significantly greater in the cases with infection compared with those without infection." (PMID 25299318, 2014). "In the present study foci of cells strongly expressing CD83 were seen at the periphery of the T cell-rich PALS but not in fully formed germinal centers following infection with MDV." (PMID 23326318, 2013). "For example, genes encoding several innate immune receptors and chemokines (such as TLR4, CD83, CCL2, CXCR4, CXCL5, IL1A and IL8)—several of which participate in the initiation of a T cell response during infection —showed increased relative expression in the BTB animal group." (PMID 22182502, 2011). "In the spleen, the CD19+ B cells and CD3+ T cells were decreased at 5 days post-infection, followed by a partial recovery at 7 days and restoration to near-normal levels at 14 days post-infection with no prominent difference between the wild type mice and CD83 KO mice." (PMID 33302987, 2020). "However, no co-localization of IE2 and CD83 was observed in the context of an HCMV-infection hinting toward an indirect mechanism for IE2-induced CD83-degradation." (PMID 28203230, 2017). "Similarly, the expression of a marker of mature antigen presenting cells (CD83) did not correlate with either infection read-out." (PMID 23865616, 2013). "Significant (p < 0.05) up regulation in cell surface expression of CD40, CD80, CD54 and MHC class II and CD86 and CD83 were observed both in LPS stimulated and H37Rv infected in comparison to negative control DC with media alone without any stimulation/infection." (PMID 21777464, 2011). "In addition, the infection of immature DCs did not induce the CD83 maturation marker expression." (PMID 20544029, 2010). "The expression of CD83 on CD19+ B cells from bone marrow and the spleen was not affected by live or UV-inactivated A/WSN/1933 virus-infection." (PMID 33302987, 2020). "After infection, CD1c+ DCs expressed HLA-DR, CD40, and CD83 (top) and produced IL-6, TNF-α, and IL-1β but not IL-23, TGF-β, or IL-12p70 (F and data not shown)." (PMID 25071784, 2014). "Flow cytometry analysis of cell surface expression markers CD40, CD54, CD80, CD83, CD86 and HLA DR in infected DC revealed significant (p < 0.05) up regulation following infection with M. tuberculosis in comparison to immature DC with no stimulation." (PMID 21777464, 2011).
infection (continued). "The infection process in these DCs does not generate significant changes in the levels of the adhesion molecule CD38 or intercellular adhesion molecule-1 (ICAM-1), and the expression of the CD83 costimulatory molecule, as compared to HSV-1-infected iDCs." (PMID 34895058, 2021). "We selected CD83, FAM63B, MYL2 and TRAM2 knockdowns for further analysis since the silencing of these four host genes resulted in increased host cell viability regardless of the strain that was employed, and these genes were not studied before in relation to S. aureus cell infection." (PMID 31659191, 2019).
cancer (40 papers, 2003 to 2026). A tumor composed of atypical neoplastic, often pleomorphic cells that invade other tissues. "In addition, CD83 polymorphisms and mutations have been reported in some cancers." (PMID 31231400, 2019). "In vitro experiments have highlighted that CD83 expression can be restored, with the hope of developing cancer vaccines capable of pharmacologically reactivating DCs/LCs and, consequentially, T cells, restoring antitumor immunity." (PMID 38791968, 2024). "A synthetic sulfolipid derived from Thalassiosira weissflogii CCMP1336 (Bacillariophyta), named SQDG18, was able to trigger an effective immune response against cancer cells to improve dendritic cell (DC) maturation and increase CD83-positive DC." (PMID 33922258, 2021). "Compared with CD83-OV and control groups, CD83-KD cancer cells showed a reduction of stemness factors, including KIT, CD44, and SOX2." (PMID 32823589, 2020). "The application of anti-CD83 antibodies or derivatives (e.g., antibody-drug conjugates) are likely to extend to the management of cancer, especially hematological malignancies." (PMID 31231400, 2019). "Regarding its future prospects for cancer therapy, the CD83-Hsp70B′ promoter system offers several interesting features." (PMID 27446966, 2016). "MDDC from cancer patients expressed significantly higher levels of HLA-DR and CD83 compared to healthy donors (cryopreserved), confirming their activated and mature phenotype." (PMID 17477875, 2007). "Mature MDDC from healthy donors and cancer patients up-regulated the expression of CD83, CD86, frequencies of IL-12+ and COX-2+ cells, and secretion of IL-8; and down-regulated CD209 expression relative to their immature counterparts." (PMID 17477875, 2007). "In fact, LPS-induced upregulation of CD80, CD86 and CD83, and the expression of IL-10 were similar in cancer patients and healthy controls." (PMID 14562018, 2003). "Indeed, the co-culture of DCs with HN-1-pretreated cancer cells significantly promoted CD83 and CD86 expression." (PMID 38970078, 2024). "MARCH1 and CD83, in addition to PD-1 and CTLA-4, are promising immune regulators that can be explored to activate host immune responses, including activation of T-helper cells and production of IFN-I that appear to be associated with successful immunotherapy for cancers." (PMID 39847577, 2025). "Moreover, isolation of CD83+ TILs may facilitate cloning of cancer neoantigen-specific TCR with optimal affinity." (PMID 36906640, 2023). "Compared to Mo‐DC from cancer patients, healthy Mo‐DC expressed higher levels of HLA‐DR, CD86, CD83, and CCR7." (PMID 38351552, 2024). "The cell densities tended to be higher in the margins compared to the benign and cancer compartments, except for the CD68+ macrophages, which tended to be more abundant in the cancer compartment and the CD83+ dendritic cells in benign tissues (p > 0.05)." (PMID 37190147, 2023). "Significantly higher expression levels of CD83 and HLA-DR, however, were observed on mature MDDC from cancer patients compared to those from healthy donors." (PMID 17477875, 2007). "qRT-PCR and ELISA assay showed that CD83 expression in SKOV3 cells was significantly upregulated after overexpression, whereas both the mRNA and protein levels of CD83 were significantly reduced in CD83-KD cancer cells." (PMID 32823589, 2020). "This targeting mechanism of ExoDS may be attributed to a variety of membrane receptors like integrin α and β chains (αMβ2), ICAM-1, MFG-E8, TNF, FasL, CD86, CD80, CD40, CD83, MHC-I, MHC-II, NKG2D, IL-15Rα, CD21, CD11c, and CCR7, which help mDC-derived exosomes identify cancer cells." (PMID 38903193, 2024).
bacterial infection (3 papers, 2020 to 2024). "In the bacterial infection model, DC expression of CD83, CD40 and CD86 recovered by D5 to baseline levels." (PMID 32180339, 2020). "Furthermore, also human polymorphonuclear neutrophils acquire CD83 expression, but not MHCII or CD86, during acute bacterial infection." (PMID 32362900, 2020).
immune dysfunction (3 papers, 2021 to 2024). "The immune dysfunction mainly contributes to the pathogenesis of PCHD, and three ceRNA networks of CD83, CXCL8, and NR4A2 may be potential candidate biomarkers for early diagnosis and treatment targets of PCHD." (PMID 36093144, 2022).
neurological disorder (1 paper, 2015). "The potential for CD83 induction by Tax1 in HTLV-I infections that leads to leukemogenesis or the onset of a neurological disorder, remains unknown." (PMID 26129803, 2015).
CD83 also shares sentences with these, for which no sentence is quoted: hematological malignancies (4 papers); squamous cell carcinoma (3); ulcerative colitis (3); bladder cancer (2); colon cancer (2); abortion (1); adenocarcinoma (1); adenoid cystic carcinoma (1); AIDS (1); allergic asthma (1); aortic aneurysm (1); autoimmune uveitis (1); autoimmune vasculitis (1); Behçet's Disease (1); benign tumors (1); carcinoma in situ (1); cervical dysplasia (1); cervicitis (1); chronic myelogenous leukemia (1); coronary artery disease (1); depression (1); desmoplastic melanoma (1); eosinophilia (1); ependymoma (1); invasive breast carcinoma (1); lip cancer (1); lip squamous cell carcinoma (1); lysosomal disorder (1); multiple myeloma (1); myocarditis (1).
A further 16 diseases each share a sentence with CD83 in 1 paper.